F13B (coagulation factor XIII B chain)
Description:
The B chain of factor XIII is not catalytically active, but is thought to stabilize the A subunits and regulate the rate of transglutaminase formation by thrombin.
Synonyms: FXIIIB
Tractability: Antibody: UniProt places it where antibodies can reach, with high confidence; its Gene Ontology location is reachable by antibodies, with high confidence; UniProt predicts a signal peptide or a membrane-spanning region.
Gene: Protein-coding gene on chromosome 1 (197,038,737 to 197,067,260, reverse strand). Ensembl gene ENSG00000143278.
Subcellular location: Secreted
Pathways (Reactome):
Hemostasis: Fibrin formation
Gene Ontology:
Biological process: blood coagulation, fibrin clot formation; blood coagulation
Cellular component: extracellular region; transferase complex
Genetic constraint (gnomAD): Loss-of-function variants: 49 observed, 69.65 expected, observed/expected ratio (o/e) 0.7, 90% interval 0.56 to 0.89. The upper end of that interval is the gene's LOEUF score, 0.89, which puts it in group 3 of 6, group 1 being the genes least tolerant of losing a copy. Missense variants: 666 observed, 712 expected, observed/expected ratio (o/e) 0.94, 90% interval 0.88 to 1. Synonymous variants: 245 observed, 236.63 expected, observed/expected ratio (o/e) 1.04, 90% interval 0.93 to 1.15.
Gene-disease validity (ClinGen):
ClinGen rates the evidence that F13B causes each of these diseases.
factor XIII, b subunit, deficiency of (autosomal recessive): Definitive.
Homologues: Orthologues: chimpanzee F13B (99% identical), macaque F13B (96% identical), dog F13B (81% identical), rabbit F13B (79% identical), pig F13B (77% identical), mouse F13b (77% identical), rat F13b (77% identical), tropical clawed frog f13b (46% identical), zebrafish cfh (23% identical), zebrafish cfhl1 (18% identical), zebrafish cfhl3 (18% identical), zebrafish cfhl2 (14% identical), and 2 more. Paralogues in human: CFH (31% identical), CFHR5 (24% identical), CSMD3 (18% identical), CSMD1 (17% identical), SVEP1 (17% identical), CSMD2 (16% identical), PAPPA (16% identical), CFHR3 (15% identical), CR2 (15% identical), PAPPA2 (15% identical), CR1 (14% identical), CFHR4 (13% identical), and 27 more.
Diseases named in the same sentence as F13B in open-access papers:
F13B is named in the same sentence as 23 diseases in open-access papers, as found by Europe PMC text mining. Sharing a sentence is not in itself a finding about the gene and the disease. The quoted sentences say what the papers report.
COVID-19 (7 papers, 2021 to 2025). A disease caused by infection with severe acute respiratory syndrome coronavirus 2. "F13B stabilizes the active transglutaminase F13A in plasma but may accumulate independently in COVID-19, where its function is less clear." (PMID 40821834, 2025). "Additionally, the levels of coagulation factor XIII B chain (F13B) in PLWH with COVID-19 were significantly lower than those in PLWH and HCs." (PMID 40568587, 2025). "Conversely, components of the coagulation cascade (SERPINA5, SERPIND1, PROC, CPB2, F13B, and KLKB1) and proteins involved in cholesterol metabolism were downregulated with the severity of COVID-19 but increased over time." (PMID 35958562, 2022).
Stroke (4 papers, 2015 to 2025). Sudden impairment of blood flow to a part of the brain due to occlusion or rupture of an artery to the brain. "Our study identified four proteins (ceruloplasmin, SERPINA1, vWF, and F13B) that commonly differentiated total stroke, IS, and ICH from healthy control subjects." (PMID 36237606, 2022). "Four proteins [ceruloplasmin, alpha-1-antitrypsin (SERPINA1), von Willebrand factor (vWF), and coagulation factor XIII B chain (F13B)] commonly differentiated total stroke, IS, and ICH from healthy control subjects." (PMID 36237606, 2022).
Venous thrombosis (4 papers, 2014 to 2023). Formation of a blood clot (thrombus) inside a vein, causing the obstruction of blood flow. "In the validated DEPs, F13B (also known as coagulation factor XIII B chain) participates in susceptibility to venous thrombosis." (PMID 33195434, 2020).
Bleeding Disorder (3 papers, 2019 to 2021). "Congenital FXIII deficiency is a rare bleeding disorder in which mutations are detected in F13A1 and F13B genes that express the two subunits of coagulation FXIII, the catalytic FXIII-A, and protective FXIII-B." (PMID 31013569, 2019).
tumor (2 papers, 2017 to 2024). "This yielded 88 genes associated with tumor grade, in which seven DEGs (C8orf33, TSNAXIP1, TM4SF1, CTH, ANXA2, KIAA1522 and LRRC1) can distinguish HCC of G3 from G1, two DEGs (CYB5A and RRAGD) can distinguish HCC of G3 from G2, and two DEGs (CFHR4 and F13B) can distinguish HCC of G3 from G4." (PMID 29123978, 2017).
cancer (1 paper, 2024). A tumor composed of atypical neoplastic, often pleomorphic cells that invade other tissues. "Recent research has highlighted the potential involvement of F13B in various cancers." (PMID 39319846, 2024). "The F13B gene has shown potential in different cancers, but its role in HCC has not been fully elucidated." (PMID 39319846, 2024).
F13B also shares sentences with these, for which no sentence is quoted: ischemic stroke (5 papers); coronary artery disease (2); hepatocellular carcinoma (2); Insulin resistance (2); myocardial infarction (2); atherosclerosis (1); cardioembolic stroke (1); coagulopathies (1); cognitive decline (1); intracerebral hemorrhage (1); intracranial hemorrhage (1); medulloblastoma (1); Sepsis (1); thrombophilia (1); thrombosis (1); thrombotic disease (1); venous thromboembolism (1).